MYC (MYC proto-oncogene, bHLH transcription factor)
Diseases named in the same sentence as MYC in open-access papers (continued):
Sharing a sentence is not in itself a finding about the gene and the disease.
cancer (continued). "While Minnelide has been shown to suppress HSP70, it can also target other critical cancer drivers including MYC." (PMID 38802657, 2024). "Taken together, these findings suggest that this combination mechanistically blocks DSB repair, resulting in the accumulation of DNA damage and the induction of apoptosis in MYC-expressing KRAS-mutant cancers." (PMID 38992694, 2024). "Disruption of CD79B and MYC showed a notably higher impact on cancer cell survival, diminishing the cell viability up to 42% and 22%, respectively." (PMID 39469218, 2024). "MYC is dysregulated in at least 70% of human cancers and is considered a primary driver of various cancers, particularly colorectal carcinomas." (PMID 39615685, 2024). "In particular, there were differences between inflammation and BiliN in cluster 5, which contains a subgroup of genes regulated by MYC, genes most downregulated in hypoxia-tolerant cancer, and pathways of oxidative phosphorylation and protein secretion." (PMID 39652576, 2024). "MYC antagonizes p27, a key cell cycle regulator, and this antagonism plays a crucial role in human cancer development." (PMID 38891892, 2024). "In this study, we report a novel marinopyrrole-derived agent, MP1 that shows desirable anti-MYC and anti-cancer activities in MYC-driven MB, both in vitro and in vivo." (PMID 38200580, 2024). "Research on MYC-related biomarkers is required to develop strategies to control cancer cell invasion in the future." (PMID 37450923, 2024). "MYC is among the most commonly deregulated genes in cancer, however, the MYC protein has been deemed “undruggable” due to intrinsically disordered regions in its structure." (PMID 39536500, 2024). "In summary, these results established that A80.2HCl as a molecule that competitively degraded MYC and as a potential therapeutic target for cancer treatment." (PMID 38424044, 2024). "A promising approach in employing in silico tools to discover pharmacological inhibition of MYC is using pharmacogenomic connectivity analysis of cancer transcriptomes and drug sensitivity data." (PMID 38390324, 2024). "MYC was also proposed to cooperate with EZH2 or YY1 to repress the transcription of onco-suppressor genes in cancer while cooperating with YAP/TAZ mainly to enhance the transcription of oncogenes." (PMID 39455556, 2024). "In cancer metabolism, MYC promotes FAO, a process occurring in mitochondria, to facilitate ATP synthesis via oxidation of fatty acids in most eukaryotic cells." (PMID 37450923, 2024). "BET proteins modulate transcription of various genes, including those synonymous with cancer, such as MYC." (PMID 38084912, 2024). "Dysregulation of protein synthesis is a common characteristic of MYC-driven cancers and is marked by increased Pol I-mediated ribosomal rDNA transcription and mTOR/eIF4E-driven mRNA translation." (PMID 39574899, 2024). "Our data comprehensively delineate TRMT61A-mediated regulation of the MYC-PD-L1 signaling axis at the translational level, unveiling a novel mechanism governing cancer progression and immunotherapy response." (PMID 38730256, 2024). "Deletion or inhibition of Gcn5 impacts growth and survival of MYC-driven cancers, including lung cancers and lymphoma, in both mouse models and human cells." (PMID 38236941, 2024). "The differentially expressed gene MYC, which controls cellular growth, proliferation, and apoptosis, is a potential therapeutic target for controlling cancer growth." (PMID 38534315, 2024). "We and several others have recently shown that short-term inhibition of CDK9 depletes short-lived transcripts and labile proteins such as MCL1 and MYC to promote cancer cell death." (PMID 38371625, 2024). "Lastly, in the growing interest of mitigating the ‘undruggable’ nature of MYC, we discuss currently available therapeutic strategies to combat MYC, a central target in the grand scheme of cancer." (PMID 38390324, 2024).
cancer (continued). "The result shows that in the high R3HDM1 expression group of almost all cancer types, cell proliferation-related signaling pathways (including MYC, mTORC1, spindle, G2M, and E2F pathways) are significantly enriched." (PMID 39376739, 2024). "For example, CDK9 inhibition is known to suppress highly expressed genes involved in cancer cell proliferation, metastasis, and treatment resistance, including MYC and MCL-1." (PMID 38172923, 2024). "MYC suppression is the molecular basis of cellular quiescence, found in embryonic stem cells (ESCs), stem cells, and cancer cells." (PMID 38418814, 2024). "More recently, increasing emphasis has been placed on the development of direct c-MYC inhibitors for targeted therapy, with clinical trials in advanced cancers currently ongoing." (PMID 38166947, 2024). "The MYC oncogene is a member of a superfamily of genes whose products are frequently activated in human cancers." (PMID 38277205, 2024). "Taken together, our findings indicate that ECGC efficiently disrupts c-MYC:TBP and c-MYC:TRRAP complex formation in cancer cells." (PMID 38424045, 2024). "The intense efforts towards developing MYC inhibitors as a cancer therapy will potentially have huge implications for the treatment of other diseases." (PMID 38510176, 2024). "MYC has also shown clear responsiveness to radiation in our previous studies in different cancer-type patients." (PMID 38256152, 2024). "MYC transcription factors regulate cell proliferation, metabolism, differentiation, and cancer genes directly and indirectly." (PMID 39563886, 2024). "Stabilization of a G-quadruplex (G4) in the promotor of the c-MYC proto-oncogene leads to inhibition of gene expression, and it thus represents a potentially attractive new strategy for cancer treatment." (PMID 38203794, 2024). "NCAPG2 promotes PCa malignancy and drives cancer stemness via the STAT3/c-MYC signaling axis, highlighting its potential as a therapeutic target for PCa." (PMID 38166947, 2024). "MYC is one of the most frequently altered oncogenes in human cancers, and its activation generally enhances cellular growth and survival." (PMID 37727135, 2024). "Recent studies on the Wnt signaling effects on reducing immune responses against HPV-induced cancer cells indicate that c-MYC upregulates PDL1 on the surface of cancer cells." (PMID 38956668, 2024). "Cancer cells with oncogenic levels of MYC need to establish ways to escape the pro-apoptotic features of MYC, and different examples of apoptosis evasion have been described across entities." (PMID 38184819, 2024). "In approximately 70% of human cancers, MYC was believed to be dysregulated, and there was compelling evidence linking aberrant MYC expression to both the initiation and maintenance of tumors." (PMID 38622518, 2024). "There are reports indicating that lncRNAs influence the regulation of cancer energy metabolism via c-MYC post-translational modifications." (PMID 39346921, 2024). "Cancers often exhibit high glucose consumption, due to higher levels of MYC, corresponding with increases in MYC-regulated glycolytic enzymes (HK2, TPI, ENO1, PKM2, and LDHA)." (PMID 37450923, 2024). "Here, we identify a novel marinopyrrole natural derivative, MP1, that shows desirable anti-MYC and anti-cancer activities in MB." (PMID 38200580, 2024).
cancer (continued). "An overexpression of PIAS1 and MYC was observed in stimulated B cells, substantial subset of prime B-cell lymphomas, and other cancer types." (PMID 38590645, 2024). "Evidence linking FGFR alterations with MYC dysregulation and the potential therapeutic relevance has been shown in different cancers." (PMID 39031286, 2024). "We then extended our study to a panel of human cancer cell lines exhibiting differential MYC/MYCN levels." (PMID 38493213, 2024). "Emerging evidence has indicated that AMBRA1 affects cancer formation, maintenance, and progression by regulating c-MYC and cyclins, which are frequently deregulated in human cancer cells." (PMID 38542788, 2024). "MYC is an oncogene that promotes cell proliferation as a transcription factor and Wnt/β-catenin signaling is activated in cancers." (PMID 38551775, 2024). "The role of the circadian clock in regulating cancer driver pathways, such as MYC and AKT1, in PDA, has been suggested by experimental models of PDA carcinogenesis." (PMID 38716727, 2024). "Consistent with these phenotypic similarities is our observation that high MYC expression levels make cancer cells dependent on the full activity of RUVBL1." (PMID 38821858, 2024). "The global genes involved in cell cycle, proliferation and differentiation of cancer cells were regulated by MYC." (PMID 38566153, 2024). "The occurrence of MYC CN gain in sinonasal adenocarcinoma has been discussed before and our results add to the topic of MYC overexpression being a significant feature in this cancer." (PMID 38711096, 2024). "Our analysis revealed significant enrichment of several cancer-related pathways, including the G2M checkpoint, E2F targets, mitotic spindle, DNA repair, spermatogenesis, and MYC targets pathways, in the high CDC6 expression group." (PMID 39052109, 2024). "MYC is unable to regulate transcription alone but works together with other genes and regulatory factors to exert effect on CSCs and cancer progression." (PMID 38561775, 2024). "So far, we have presented several pieces of evidence to support the concept that SP1, HIF1A, and MYC collaborate to promote cancer development and that inhibitors of these transcription factors should induce strong anticancer activity." (PMID 39590335, 2024). "Preliminary evidence suggests that interactions between SWI/SNF and oncoprotein transcription factors such as MYC, AP-1, TAZ, YAP or mTOR are implicated in various cancers." (PMID 39471843, 2024). "This displacement leads to the suppression of MYC transcription and inhibits tumor growth across various cancer models." (PMID 39770515, 2024). "One of the most commonly upregulated pro-oncogenic factors in cancer is MYC, which is the master regulator of a vast transcriptional program crucial for cancer progression." (PMID 39217152, 2024). "A representative example of complex lncRNA-mediated regulation that relates to carcinogenesis is CCAT1-L, which regulates the well-known oncogene MYC (myelocytomatosis oncogene), an oncoprotein that is overexpressed in various cancers." (PMID 39123456, 2024). "The oncogene c-MYC plays vital roles in the progression of many human cancers through transcriptional upregulation to facilitate the malignant behaviours of cancer cells." (PMID 38886753, 2024). "Despite this, studies on other cancers have indicated another possible therapeutic relevance of MYC expression levels in tumors with FGFR alterations." (PMID 39031286, 2024). "As mentioned in the introduction, MYC deregulation has been reported in approximately 70% of all human cancers." (PMID 39164274, 2024). "Meanwhile, it was shown by several systems analyses that SP1, HIF1A, and MYC functioned as master regulators of cancer development." (PMID 39590335, 2024). "The MYC oncogenic transcription factor is overexpressed in many cancer patients and regulates cell cycle, self-renewal, survival, cell growth, metabolism, protein synthesis, differentiation, and tumorigenesis." (PMID 38462658, 2024).
cancer (continued). "Rapidly proliferating cancer cells inherently produce increased levels of oncogenic MYC, resulting in diminished genomic stability." (PMID 39563886, 2024). "In advanced cancer cells, chemotherapy and radiation induce genomic instability, prompting oncogenic MYC to develop an efficient DNA repair mechanism." (PMID 39563886, 2024). "The DNA repair pathway, E2F signaling pathway, G2M checkpoint signaling pathway, mitotic spindle signaling pathway, and MYC signaling pathway exhibited positive correlations with various types of cancers." (PMID 38495498, 2024). "c-MYC is a master transcription factor that binds the E-box sequences with overexpression in >74% of human cancers." (PMID 39123391, 2024). "Cancer cells with high MYC levels tend to be in the late stages or return after treatment, which suggests that there must be more DNA damage in these cells." (PMID 39563886, 2024). "The proto-oncogene MYC is overexpressed in the majority of cancers and can potentially affect the expression of all genes." (PMID 38184819, 2024). "Given the significant role of the MYC gene in cancer initiation, maintenance, and progression, targeting c-Myc represents a promising approach." (PMID 38594783, 2024). "Recent reports suggest that the inhibition of MYC is accompanied by intracellular lipid droplet accumulation in cancer cells as a direct consequence of mitochondrial dysfunction." (PMID 38893482, 2024). "These DEGs associated with Wemics‐detected DMRs were enriched for several cancer‐related pathways, such as MYC activity, regulation of epithelial cell proliferation, negative regulation of growth, and cell fate commitment." (PMID 38544480, 2024). "Over the past several years, NSD3S has been established as an adaptor protein for important drivers of cancer, such as MYC, BRD4, and CHD8." (PMID 38256018, 2024). "The uropathogenic Escherichia coli protease, Lon, can reduce c-MYC expression in animal and human models and improve the prognosis of patients with c-MYC-induced cancer." (PMID 37450923, 2024). "For this, the MYC family has been recognized as one of the most altered in various tumor types, albeit MYC is the most deregulated gene in human cancer." (PMID 39596100, 2024). "One of the most investigated molecular targets for anticancertherapyis the proto-oncogene MYC, which is amplified andthus overexpressed in many types of cancer." (PMID 39741863, 2024). "In this study, a series of new molecules, KB-0742, a potent, selective, orally bioavailable small molecule inhibitor of CDK9 for MYC-dependent cancers, was relied upon." (PMID 39498375, 2024). "White men had higher activity of MYC-related pathways, while Black men showed increased activity of inflammation, steroid hormone responses, and cancer progression-related pathways." (PMID 39044302, 2024). "In samples from more than 20 cancer types, the genes regulated by eRNAs were found to be involved in canonical cancer pathways, including MYC, KRAS proto-oncogene (KRAS), and DNA repair pathways." (PMID 38863031, 2024). "In medulloblastoma, the transcriptional inhibition of MYC by OTX-015 alters cancer glycolysis and amino acid metabolism." (PMID 38390324, 2024). "This technology is a platform to safely engineer transcripts and therapeutic genes as shown for c-MYC in cancer treatments." (PMID 39123391, 2024). "Over the years, O-GlcNAcylation has been linked to multiple cancer hallmarks through the modification and modulation of many cancer-relevant proteins such as FOXM1, c-MYC, β-catenin, snail and NF-kB." (PMID 39413067, 2024). "BRD4 and CDK9 have complementary and intimately connected roles in enhancing oncogenic gene expression programs in a variety of cancer types, especially in the context of MYC-driven tumors." (PMID 39117800, 2024). "At the same time, MYC inhibits apoptosis, allowing cancer cells to survive longer and preventing the natural elimination of abnormal cells." (PMID 38637125, 2024).
cancer (continued). "Together, the abundance of MYC and a balance of these transactivators or transrepressors, dictate the fate of cancer progression." (PMID 38390324, 2024). "c-MYC is a transcription factor that is constitutively and aberrantly expressed in over 70% of human cancers." (PMID 38791215, 2024). "When abnormally expressed, MYC gives rise to the oncogene MYC, which drives cancer development and metastasis and is present in up to 70% of human cancers." (PMID 39769320, 2024). "About 70% of human cancers, including breast, bone, brain, B-cell lymphoma, colon, cervix, lung, pancreas, and prostate tumors have various MYC alterations that correlate with poor prognosis and increased disease aggressiveness." (PMID 39457457, 2024). "In this study, we found that CREPT, an oncoprotein ubiquitously overexpressed in various cancers, serves as a critical mediator of MYC in initiating gene transcription." (PMID 39615685, 2024). "The PCAT1 ncRNA is known to repress BRCA2, activate MYC, promote cell proliferation, and is upregulated in prostate, colorectal, and other cancers." (PMID 38981681, 2024). "In this study, we presented a conclusive evaluation of CNOT3 functional interaction with c-MYC, a critically important oncogene in cancer." (PMID 38491013, 2024). "Consistent with this, the enrichment in G2M checkpoint, E2F transcription factors, and MYC targets suggest that clustered ceRNA interactions are involved in the function of cancer cell proliferation." (PMID 38627780, 2024). "Inspired by the demonstration that the expression of a cancer gene (MYC) can be down regulated by a G4 ligand led to an emphasis on promoter G4 targeting by NDs." (PMID 39125057, 2024). "The c-MYC proto-oncogene predominantly controls cell proliferation, apoptosis, and drug resistance in various cancer types such as cervical, breast, and lung cancers." (PMID 38902227, 2024). "KRAS with the G12D mutation modulates translation via the MNK/eIF4E pathway and results in sustained expression of c-MYC, a common proto-oncogene involved in many cancers." (PMID 38481800, 2024). "Targeting MYC presents a promising avenue in cancer therapeutics owing to its ubiquitous dysregulation as a driver gene in human cancers." (PMID 39431237, 2024). "Up to 28% of all tumors exhibit gene amplification of one of the MYC isoforms (MYCN, MYCL or MYC), defining MYC genes as the most frequently amplified oncogene family across human cancers." (PMID 37935464, 2024). "Nevertheless, MYC was frequently ranked second in cancer types, with EGR1 as the top-ranking candidate." (PMID 39766097, 2024). "MYC regulation of glutamine catabolism can have varying outcomes, according to the different metabolic requirements of diverse cancer types." (PMID 37450923, 2024). "We also confirmed that the STK16 inhibitor significantly suppressed c-MYC expression and the proliferation ability of cancer cells in both in vitro and in vivo experiments." (PMID 38622518, 2024). "Further investigations on an expanded array of KRAS- and/or MYC-dependent cancers are warranted to support the use of PPRHs in combination." (PMID 39457457, 2024). "c-MYC is significantly activated in approximately 70% of human cancers via genetic, epigenetic, and post-translational mechanisms, including the process of maintaining protein stability." (PMID 39513905, 2024). "The canonical CMS2 subtype is characterised by an activation of the WNT and MYC pathways, which are involved in the maintenance and growth of cancer stem cells." (PMID 38339195, 2024). "This positioned MYC as one of the most attractive targets for the development of cancer therapeutics." (PMID 38622518, 2024).